PDGFRL (platelet derived growth factor receptor like)
Synonyms: PRLTS; PDGRL
Tractability: Antibody: UniProt places it where antibodies can reach, with high confidence; UniProt predicts a signal peptide or a membrane-spanning region; its Gene Ontology location is reachable by antibodies, with medium confidence.
Gene: Protein-coding gene on chromosome 8 (17,576,433 to 17,644,071, forward strand). Ensembl gene ENSG00000104213.
Subcellular location: Secreted
Subcellular location (Human Protein Atlas): Golgi apparatus; Nucleoli; Nucleoplasm; Predicted to be secreted
Gene Ontology:
Molecular function: platelet activating factor receptor activity; platelet-derived growth factor beta-receptor activity; platelet-derived growth factor receptor activity
Biological process: cellular response to platelet-derived growth factor stimulus; G protein-coupled receptor signaling pathway; platelet-derived growth factor receptor signaling pathway; platelet-derived growth factor receptor-beta signaling pathway
Cellular component: extracellular region
Genetic constraint (gnomAD): Loss-of-function variants: 37 observed, 29.65 expected, observed/expected ratio (o/e) 1.25, 90% interval 0.96 to 1.64. The upper end of that interval is the gene's LOEUF score, 1.64, which puts it in group 6 of 6, group 1 being the genes least tolerant of losing a copy. Missense variants: 565 observed, 393.9 expected, observed/expected ratio (o/e) 1.43, 90% interval 1.34 to 1.54. Synonymous variants: 194 observed, 159.99 expected, observed/expected ratio (o/e) 1.21, 90% interval 1.08 to 1.37.
Homologues: Orthologues: macaque PDGFRL (97% identical), pig PDGFRL (90% identical), mouse Pdgfrl (89% identical), dog PDGFRL (89% identical), guinea pig PDGFRL (88% identical), rat Pdgfrl (87% identical), rabbit PDGFRL (80% identical), chimpanzee PDGFRL (73% identical), tropical clawed frog pdgfrl (68% identical), zebrafish pdgfrl (56% identical).
Diseases named in the same sentence as PDGFRL in open-access papers:
PDGFRL is named in the same sentence as 24 diseases in open-access papers, as found by Europe PMC text mining. Sharing a sentence is not in itself a finding about the gene and the disease. The quoted sentences say what the papers report.
breast carcinoma (5 papers, 2008 to 2024). "Intriguingly, PDGFRL exhibits cell type-dependent roles, functioning as an oncogene in chondrocytes and as a tumor suppressor gene in breast cancer cells." (PMID 38848147, 2024). "Recently, an in-depth study of the region using microcell-mediated chromosome transfer found that indeed PDGFRL expression is decreased in the majority of breast cancer cells." (PMID 18366601, 2008). "PDGFRL is located in chromosome 8p22-8p21.3, where multiple studies have suggested the existence of a putative breast cancer tumor suppressor gene." (PMID 18366601, 2008). "For example, two hub genes of modules, PDGFRL and CD163, also show very weak expression similarities across all seven breast cancer datasets: the average Pearson correlation between these two genes is only 0.24." (PMID 18366601, 2008). "In particular, we identified a breast cancer specific network module that involved in tumor suppression via platelet-derived growth factor (PDGF)-like signaling, more importantly, a hub gene PDGFRL that may play an important role in this tumor suppressor module." (PMID 18366601, 2008).
colorectal cancer (2 papers, 2021 to 2023). A primary or metastatic malignant neoplasm that affects the colon or rectum. "OMIM disease analysis also revealed two genes—MCC and PDGFRL—with an impact on the colorectal cancer process." (PMID 37762215, 2023). "PDGFRL, which is regarded as a tumor-suppressor gene, inhibits the proliferation and invasion of colorectal cancer cells in vitro." (PMID 34604236, 2021).
endometriosis (2 papers, 2022 to 2025). The growth of functional endometrial tissue in anatomic sites outside the uterine body. "Furthermore, PDGFRL was identified as a potential biomarker for endometriosis through analysis of GEO datasets, development of a diagnostic model, and RT-qPCR validation, also provide new insights into endometriosis treatment." (PMID 40476267, 2025). "Related studies manifest PDGFRL is related to the steroid hormone feedback mechanism of the reproductive system of chickens, and there are few reports on the relationship with endometriosis." (PMID 36524127, 2022). "This suggests that PDGFRL should play a role in the pathogenesis of endometriosis, and the specific mechanism needs further study." (PMID 36524127, 2022).
breast tumor (1 paper, 2008). "Our module showed the breast tumor specific co-expression between PDGFRL and collagens COL3A1, COL5A2 and COL6A3." (PMID 18366601, 2008). "Importantly, we have discovered a potential tumor suppressor network particularly active in breast tumors, and provide compelling evidence that the hub gene PDGFRL is a true tumor suppressor gene." (PMID 18366601, 2008).
chondrosarcoma (1 paper, 2025). A malignant cartilaginous matrix-producing mesenchymal neoplasm arising from the bone and soft tissue. "Overexpression of PDGFRL has been shown to impede the proliferation of HCS-2/8 in human chondrosarcoma cells." (PMID 40476267, 2025).
gastric cancer (1 paper, 2025). A primary or metastatic malignant neoplasm involving the stomach. "The findings derived from analyses utilizing data from the GEO and TCGA databases indicate that PDGFRL exhibits strong predictive capabilities for overall survival in gastric cancer across five independent cohorts." (PMID 40476267, 2025).
gastrointestinal stromal tumor (1 paper, 2025). "Compared with a gastrointestinal stromal tumor, myxoid liposarcoma, and sarcomas with complex genomics, PDGFRL expression rates in SS are low; however, its levels have not been analyzed with regard to histological subtype." (PMID 41155410, 2025).
hepatocellular carcinoma (1 paper, 2010). A malignant tumor that arises from hepatocytes. "For example, LOH is a frequent event for BRCA1 in breast and ovarian cancers, for MSH3 in breast, bladder and non-small cell lung cancers, and for PDGFRL in sporadic hepatocellular carcinomas, colorectal and non-small cell lung cancers." (PMID 21108794, 2010).
keloid (1 paper, 2022). An irregularly shaped, elevated mark on the skin caused by deposits of excessive amounts of collagen during wound healing. "Considering that PDGFRL exhibits significant sequence similarity with the extracellular domain of PDGFR, which contributes to keloid formation, it follows that PDGFRL may also be involved in the keloid scarring." (PMID 35435317, 2022). "PDGFRL was identified as one of the unique proteins expressed in keloid scar tissues." (PMID 35435317, 2022). "As one of the uniquely expressed proteins in keloid scars, PDGFRL could be considered as a potential candidate for the diagnosis and treatment of keloids." (PMID 35435317, 2022). "The fact that we observed the upregulation of FBLN1, FN1, and PDGFRL in keloids in our proteomic profiles enhances the possibility of this hypothesis." (PMID 35435317, 2022). "We identified 206 proteins that showed significant differences in expression between keloid scars and normal skin tissues, including RCN3, RCN1, CALU, and PDGFRL which may play an import role in keloid formation." (PMID 35435317, 2022). "PDGFRL may show a redundant function or a differential function with PDGFRB; thus, PDGFRL may also be a potential therapeutic target of keloids." (PMID 35435317, 2022).
meningioma (1 paper, 2017). A generally slow growing tumor attached to the dura mater. "AQP1, FRZB, PDGFRL, and PECAM1 were consistently underexpressed in meningioma samples; MEDAG, MYC, PAMR1, PDPN and PERP were consistently overexpressed in nearly every meningioma sample by both measurements." (PMID 29073243, 2017). "Five genes that were down-regulated in the meningiomas compared to the control tissue included AQP1 (aquaporin 1), FRZB (Frizzled b), PECAM1 (platelet and endothelial cell adhesion molecule 1), PDGFRL (platelet-derived growth factor receptor-like), and FBLN2 (fibulin 2)." (PMID 29073243, 2017).
tumor (12 papers, 2007 to 2025). "It should also be remembered that PDGFRL, which is also a specific agonistic ligand for PDGFRβ, is known to have potential tumor suppressor activity." (PMID 33524869, 2021). "FN1 functionally connects a pair of coexpressed glycoproteins, FBLN1 and FSTL1, and SPARC is connected to IGFBP7, a tumor suppressor, which creates a functional link between a candidate tumor suppressor, PDGFRL, and a mesenchymal factor, FSTL1." (PMID 24944582, 2014). "PDGFRL, a specific PDGFRβ agonist, has been suggested to exert a tumor-suppressive effect." (PMID 41155410, 2025). "Here by adopting a network perspective, we have identified their interrelationships and, particularly, a hub gene PDGFRL that may play an important role in this tumor suppressor network." (PMID 18366601, 2008). "Here by adopting a network perspective, we have identified their interrelationships and a gene (PDGFRL) that may play a central role in this tumor suppressor network." (PMID 18366601, 2008). "The reverse transcription real-time PCR assay revealed higher expression of tumor markers CDKN2A, EGFR, and PDGFRL in monophasic SS." (PMID 41155410, 2025). "The downregulation of PDGFRL expression in FTC aligns with findings from prior research, suggesting its role as a tumor suppressor gene." (PMID 40476267, 2025). "The reverse transcription real-time PCR assay revealed higher expression of tumor markers CDKN2A, EGFR, and PDGFRL in monophasic SS compared to biphasic tumors." (PMID 41155410, 2025).
cancer (8 papers, 2008 to 2025). A tumor composed of atypical neoplastic, often pleomorphic cells that invade other tissues. "Indeed, mutations in PDGFRL have been found in individual cancer samples." (PMID 18366601, 2008). "Results from these assays showed significant reductions in cell proliferation, migration, and invasion in PDGFRL-silenced AGS cells compared to controls, suggesting that PDGFRL may act as a cancer promoter in this context." (PMID 38848147, 2024). "Currently, our understanding of PDGFRL in cancer biology is limited." (PMID 38848147, 2024). "The number of selected genes by semi-supervised learning method is less than the single Cox and AFT model, but includes some genes which are significantly associated with cancer and cannot be selected by the two single Cox and AFT models, such as GDF15, ARHGDIB and PDGFRL." (PMID 26932592, 2016). "The markers GPX3, PDGFRL, RGS2, and SERPINE1 were found to be significantly increased in the high-risk group, suggesting that all of these markers may be implicated in the malignancy processes for STAD patients and may be cancer-promoting factors." (PMID 36199800, 2022). "Apart from the more immunosuppressive microenvironment, monophasic tumors are characterized by higher expression of cancer-related genes CDKN2A, EGFR, and PDGFRL, which can be considered as potential targets for treatment." (PMID 41155410, 2025). "Monophasic tumors are characterized by higher expression of cancer-related genes CDKN2A, EGFR, and PDGFRL, which can be considered as potential targets for treatment." (PMID 41155410, 2025). "In STAD patients, the genes GPX3, PDGFRL, RGS2, and SERPINE1 may be connected to the cancer process." (PMID 36199800, 2022). "The products of several genes from our potential cell surface list are suspected of playing key roles in more general cancer-related activities such as immunosuppression/evasion (CD14 and CD86), cell migration (ICAM, CDH11) and proliferation (TGFB1, PMEPA1, PDGFRL, SLC19A3)." (PMID 27363029, 2016).
PDGFRL also shares sentences with these, for which no sentence is quoted: COVID-19 (2 papers); basal cell carcinoma (1); cardiovascular diseases (1); colon cancer (1); follicular thyroid carcinoma (1); invasive carcinoma (1); myxoid liposarcoma (1); non-small cell lung carcinoma (1); osteoporosis (1); ovarian carcinoma (1); prostate carcinoma (1); sarcoma (1).